GATA3 (GATA binding protein 3)
Diseases named in the same sentence as GATA3 in open-access papers (continued):
Sharing a sentence is not in itself a finding about the gene and the disease.
breast carcinoma (continued). "Herein, we further demonstrate that KDM4B is an AR/GATA3 target gene in ER- and ER+ breast cancers, supporting the concept of AR co-operating with ER signaling to promote differentiation in ER+ disease and independently promoting differentiation in ER- disease." (PMID 38317241, 2024). "Reciprocal pull down of GATA3 was associated with detection of AR in a DHT-dependent manner in the ER- breast cancer cell lines but not the ER+ lines." (PMID 38317241, 2024). "Taken together, GATA3 appears as a favorable prognostic factor, but the question of its importance as an independent factor needs further elucidation, considering the choice of cut-off for positivity as well as the influence of breast cancer therapy." (PMID 39242600, 2024). "For example, targeting the ZPO2/GATA3 signaling axis in breast cancer or modulating GATA3-AS in liver carcinoma could provide effective treatment options." (PMID 39768217, 2024). "While GATA3 is also expressed in a high percentage of breast cancers, its expression can be seen in other tumor types, such as urothelial carcinomas or salivary gland tumors, which may impact the diagnosis." (PMID 39518009, 2024). "Therefore, in the context of ER+ breast cancer, the interaction between AR and GATA3 likely plays a role in reprogramming ER signaling to inhibit proliferation and promote terminal differentiation." (PMID 38317241, 2024). "Clusters in which breast cancer was exclusive or dominant contained PIK3CA or GATA3 genes." (PMID 39040139, 2024). "We previously demonstrated that loss of p18, a cell cycle inhibitor, in mice induces luminal-type mammary tumors, whereas depletion of either Brca1 or Gata3 in p18 null mice leads to basal-like breast cancers (BLBCs) with activation of epithelial-mesenchymal transition (EMT)." (PMID 38627785, 2024). "We then tested whether depletion of GATA3 in mammary tumor cells impairs DNA damage response to estrogen, a hormone fluctuating during the menstrual cycle and inducing DNA DSBs." (PMID 38627785, 2024). "We treated Brca1+/− or Gata3+/− mammary tumor cells with olaparib (OLA), a PARP inhibitor." (PMID 38627785, 2024). "To test this hypothesis, we performed IHC analysis with the antibody against γH2AX, a marker for DNA DSBs, in mammary tumors spontaneously developed in p18−/− and p18−/−;Gata3+/− mice." (PMID 38627785, 2024). "We also demonstrated that GATA3 functions downstream of BRCA1 to suppress EMT in breast cancer." (PMID 37353480, 2023). "Receiver operating characteristic curves (ROC) confirmed a significantly improved prognostic performance of PR, AR, and GATA3 expression quantified by our approach for automated breast cancer detection compared to an assessment of these markers without using the approach (each p < 0.0197)." (PMID 38137396, 2023). "In breast cancer, GATA3 induces tumor differentiation in undifferentiated carcinomas." (PMID 37629741, 2023). "Like FOXA1, GRHL2 may act as a pioneer factor, promoting chromatin accessibility and GRHL2 has been found to co-occupy enhancer elements with FOXA1, GATA3, and ER⍺ to regulate ER⍺ signaling output in hormone receptor positive breast cancer." (PMID 36691073, 2023). "There is a significant upregulation of GATA3 protein expression levels in breast cancer tissues." (PMID 37900131, 2023). "High GATA3 expression is a feature of luminal-type breast cancer and predicts better survival." (PMID 37353480, 2023). "Given that patients have a history of breast cancer, 2 breasts specific markers, GATA3 (−), GCDFP-15 (−), and ER (−), PR (−), combined with the pathological form of patients with primary breast tumors and hormone receptor status, the recurrence and metastasis of breast cancer was excluded." (PMID 36930116, 2023). "Increased expression of GATA3 is the most widely used biomarker for breast cancer." (PMID 37373190, 2023).
breast carcinoma (continued). "To determine whether our mouse genetic analysis models human breast cancers, we queried the expression of GATA3 and AP-1 in breast cancer patient sample sets." (PMID 37353480, 2023). "The GATA3 gene is often overexpressed in breast cancer and is widely used to support a diagnosis." (PMID 36909571, 2023). "Similarly, immunohistochemical expression of GATA-3 in human breast cancer showed a direct correlation with that of ER, as the marker was related to the ER− phenotype, which is characteristic of poorly-differentiated aggressive tumors." (PMID 37483298, 2023). "Finally, our results in Breast-AdenoCA also highlighted some genes that are specifically known to be frequently mutated in breast cancer, including PIK3CA, CDH1, GATA3, and MAP2K4." (PMID 38062391, 2023). "ASH2L upregulates GATA3‐induced transcription of ESR1 in breast cancer cells." (PMID 37974198, 2023). "Furthermore, GLS2 that is upregulated by GATA3 in luminal-subtype breast cancer modulated the resistance to GLS inhibitors such as BPTES." (PMID 37249801, 2023). "The present study evaluated GATA-3 expression in spontaneous mammary tumors of female dogs in accordance with degree of malignancy, as defined by tumor histopathological and clinical classification, and the relationship between this expression and survival rates." (PMID 37483298, 2023). "The use of semi-quantitative or qualitative methods to assess GATA-3 expression may contribute to the divergence of results in terms of the relationship between prognostic factors and GATA-3 in breast cancer in women." (PMID 37483298, 2023). "Together, our results indicate that in mammary tumor cells GATA3 directly activates the transcription of FOS to maintain their luminal and epithelial features while concurrently repressing the transcription of FOSL1 to suppress aberrant mesenchymal differentiation, i.e., inhibiting EMT." (PMID 37353480, 2023). "By using these mouse models, we investigated how GATA3 regulates the AP-1 transcription factor and whether AP-1 is essential for GATA3 deficiency-activated EMT in mammary tumor development and progression." (PMID 37353480, 2023). "Moreover, similar to mammary tumors in women, this study showed that GATA-3 expression was inversely proportional to the malignancy potential of mammary tumors in dogs." (PMID 37483298, 2023). "The incidence of mammary tumor metastasis in p18mt;Gata3+/− mice was underestimated." (PMID 37353480, 2023). "Recently, the implication of GATA3 in breast cancer has emerged." (PMID 35804829, 2022). "GATA3 mutant breast cancer patients had lung, lymph nodes, and brain metastases." (PMID 35154280, 2022). "GATA-3, estrogen, and progesterone receptors are helpful in diagnosing the origin of breast cancer." (PMID 35740683, 2022). "GATA3, standing for GATA binding protein 3, contains two GATA-type zinc fingers at the structural level and is closely associated with the progression of various cancers, including breast cancer." (PMID 35647011, 2022). "GATA3 is a known transcription factor that controls the expression of several genes in the breast cancer; therefore, we presumed that GATA3 could regulate the transcription of MFNG." (PMID 35804829, 2022). "For example, breast cancer cells specifically express TF ESR1, together with its cooperating TF GATA3, inducing global transcriptional network changes by mediating enhancer accessibility as well as eRNA expression in breast cancer cells to promote tumorigenesis." (PMID 36232885, 2022). "Enhancer reprogramming which promotes phenotypic plasticity and endocrine therapy resistance in breast cancer has also been observed to be mediated by the coordinated role of GATA3 and AP1 TFs which re-organize enhancer landscape promoting tumor phenotypic plasticity." (PMID 35774123, 2022).
breast carcinoma (continued). "In breast cancer cells, PARP1 competes with histone H1 to maintain transcription of the oncogene CCND1 (encoding cyclin D1), and also acts as a transcriptional coactivator of GATA binding protein 3 (GATA3), thus promoting the transcription of CCND1." (PMID 36566215, 2022). "Since MGP and TRPS1 showed high expression in luminal A/B, HER2-enriched, TNBC/basal-like, and normal-like subtypes according to the PAM50 subtyping, we selected MGP, TRPS1, and GATA3 for further validation in 1201 cases of breast carcinoma of different subtypes and normal breast tissues." (PMID 36284362, 2022). "GATA-3 was highly expressed in both breast cancer and urothelial carcinoma." (PMID 36254025, 2022). "GATA-3 is a transcription factor important in the differentiation of breast epithelia, urothelial, and subsets of lymphocytes and hence can be utilised in patients with a known history of breast cancer." (PMID 35328664, 2022). "As shown, GATA3 is a TFMarker which can regulate the T Marker PIP in breast cancer." (PMID 34986601, 2022). "Our data show that the expression of POLR3G in breast cancer samples was negatively correlated with that of eight out of ten genes (GATA3; XBP1; AGR2; SIDT1; AR; SPDEF; FOXA1; MLPH) in a list of signature genes most differentially expressed in luminal A compared to basal-like tumors." (PMID 36497214, 2022). "FOXA1 binding sites are known to define lineage-specific enhancers in luminal breast cancer cells and several luminal-specific transcription factor motifs (GATA3, TRPS1, etc.) were also significantly enriched in the set of differentially accessibly ATAC-seq sites." (PMID 35353838, 2022). "Moreover, GATA3 was further identified as a core TF and has high expression in breast cancer (right)." (PMID 34986601, 2022). "Being a tumor-suppressor gene, the damage of GATA3 in breast cancer resulted in a poor prognosis." (PMID 36140219, 2022). "Both FOXA1 and GATA3 TFs are known markers in breast cancer." (PMID 35331302, 2022). "Since GATA3 regulates microRNA expression in the breast cancer, we sought to determine whether GATA3 could control miR205-5p expression to cooperatively co-suppress MFNG expression." (PMID 35804829, 2022). "To better understand the roles of GATA3 mutants in breast cancer cells, we established three luminal breast cancer cell lines stably expressing X308 splice site deletion mutant (Splice del), C321 frameshift mutant (C321fs), and A333 frameshift mutant (A333fs), respectively." (PMID 35154280, 2022). "Consistent with the findings derived from mice, in human breast cancers, loss of p18 and amplification or overexpression of cyclin D and CDK4 are frequently detected in luminal type tumors whereas loss of GATA3 expression and loss or mutation of Rb are key features of BLBCs 8, 27-31." (PMID 34976209, 2022). "GATA3 is a transcription factor and is known to be involved in multiple developmental pathways and human diseases such as normal mammary gland development, breast cancer progression, and T cell differentiation." (PMID 35154280, 2022). "To determine whether and how depletion of GATA3 in established mammary tumor cells promotes basal differentiation and impacts tumor progression, we took advantage of the newly established Gata3 positive murine luminal type tumor model system." (PMID 34976209, 2022). "Cooperates with GATA3 to control enhancer reprogramming and therapy resistance in breast cancer." (PMID 34616687, 2021). "We then determined the expression of GATA3 in human breast cancer cell lines and found that GATA3 mRNA and protein levels were high in BRCA1 proficient cells (T47D and MCF7) and low or undetectable in BRCA1 deficient (BT20, MDA-MB231, SUM149, and HCC1937) cells." (PMID 34373738, 2021).
breast carcinoma (continued). "However, due to growth defects induced by long-term loss of Gata3 and apoptosis caused by acute loss of Gata3 in differentiated tumor cells 15, 32, 33, it remains elusive if Gata3 loss regulates EMT in breast cancer development and progression." (PMID 34373738, 2021). "Interestingly, we found a novel co-regulation of FOXA1 and GATA3 with a common binding partner of AP-1 complex like breast cancers that appears to drive activity of distal enhancers, but not promoters." (PMID 33858483, 2021). "FOXA1 and GATA3 have been shown to be consistently expressed in the luminal subtype of breast cancer, indicating the presence of a co-modulatory loop that might contribute to the maintenance of the luminal phenotype." (PMID 34094972, 2021). "We demonstrated that knockdown of GATA3 in T47D human breast cancer cells or overexpression of WT Gata3 in Gata3 deficient mouse mammary tumor cells did not cause significant change of BRCA1 mRNA levels." (PMID 34373738, 2021). "Importantly, forced GATA3 expression in GATA3-negative, immature breast carcinoma cells induced tumor differentiation and reduced malignant properties." (PMID 33803938, 2021). "It has been reported that the TF network composed of estrogen receptor alpha (ESR1), FOXA1, and GATA3 may control the gene expression pattern in luminal breast cancer." (PMID 34249704, 2021). "GATA binding protein 3 (GATA3) is one of the important genes involved in breast cancer development." (PMID 33462316, 2021). "Thus, we undertook the current study to evaluate the expression of GATA3 and its prognostic value in a large series of breast carcinomas (BCs) with long-term follow-up." (PMID 33800667, 2021). "It has been debatable whether GATA3, which is extensively investigated in breast cancer, functions to suppress or promote cancer." (PMID 34595169, 2021). "Highlighting these genes differentially marked with the broad H3K4me3 domain in MDA-MB-231 cells (SPRY4) and in MCF7 cells (FOXA1 or GATA3) demonstrates the importance of these genes in maintaining the cellular properties of these two different types of breast cancer cells." (PMID 34238359, 2021). "Furthermore, subgrouping classifiers for breast cancer genes such as GATA3 and MAP3K1 which had been found to be divergent from the corresponding gene-wide classifiers preserved their divergence in the transfer setting." (PMID 33957863, 2021). "However, the enrichment for ESR1, FOXA1, and GATA3 was stronger for ER-positive CCVs than for ER-negative or overall breast cancer CCVs." (PMID 34439109, 2021). "To test this hypothesis, we compared the mammary tumors developed in Gata3+/- and Brca1+/- mice under the same p18mt background." (PMID 34373738, 2021). "Importantly, when compared with p18mt tumors, both p18mt;Gata3+/-and p18mt;Brca1+/-mammary tumors more frequently metastasized to the lungs, and the lung metastasis were also enriched with mesenchymal-like cells." (PMID 34373738, 2021). "To determine the similarity of cellular phenotype of Brca1 and Gata3 deficient tumor cells, we generated five p18mt;Brca1+/-, five p18mt;Gata3+/-, and three p18mt tumor cell lines, each of which was derived from a primary mammary tumor developed in an individual mouse." (PMID 34373738, 2021). "Murine studies have shown that GATA3 expression is lost as luminal epithelial cells become less differentiated during breast cancer progression and low GATA3 expression has been strongly associated with histological grade and positive lymph nodes, both of which are indicators of poor prognosis." (PMID 33298139, 2020). "In addition, correlation of NF-κB and GATA3 expressions was confirmed in consecutive human breast cancer tissues by IHC analysis." (PMID 32461377, 2020).
breast carcinoma (continued). "A recent study by Li and colleagues identified that GATA3 could reduce extracellular ATP (eATP) in the breast cancer microenvironment by upregulating ectonucleoside triphosphate diphosphohydrolase 3 (ENTPD3), an eATP hydrolytic enzyme." (PMID 33298139, 2020). "In addition, the absence of GATA3 was found to be positively correlated with the highly aggressive nature of breast cancer, for this, research suggested that GATA3 fundtions together with estrogen receptors in producing an inhibitory effects on breast cancer." (PMID 32760217, 2020). "Our results indicate that lncRNA LOC645166 /NF-κB/ GATA3 might be a candidate prognostic biomarker and a target for reversing adriamycin resistance in breast cancer." (PMID 32461377, 2020). "Initial studies in T cells postulated that the C-terminal region of GATA3, between residues 261 and 315, is critical for proteasomal degradation, and further work in ER-positive breast cancer cells subsequently identified serine residue 308 as the critical site." (PMID 33298139, 2020). "GATA3 functions as a critical transcriptional activator of E-cadherin to impede the phenotype transition between epithelial and mesenchymal cells, and suppresses metastasis and alters the tumor microenvironment in breast cancer." (PMID 32787800, 2020). "In addition, lncRNA LOC645166 exerts these functions by binding NF-κB to the promoter region of GATA3, thereby increasing GATA3 expression and promoting breast cancer chemoresistance." (PMID 32461377, 2020). "By adding different concentrations of ATP to the cell culture medium, we discovered that eATP promoted migration and colony formation by MDA-MB-231 cells and that the eATP-induced progression of breast cancer was partially reversed by the increased expression of GATA3." (PMID 31754326, 2019). "The potential explanation for this phenomenon may be that GATA3 acts differently in various breast cancer subtypes." (PMID 30872657, 2019). "By analyzing the functions of 20 genes with the greatest variation in differential expression, we discovered that ENTPD3 may be a key downstream molecular regulator of GATA3 that inhibits breast cancer metastases." (PMID 31754326, 2019). "Thus, the up-regulation of ENTPD3-mediated GATA3 not only inhibits breast cancer cell motility, but also modulates the tumor microenvironment to repress breast cancer cell metastasis." (PMID 31754326, 2019). "Over 80% of FOXA1 and GATA3-positive breast carcinomas belonged to the luminal A subtype." (PMID 30819139, 2019). "These significantly enriched GO terms and KEGG pathways could help us deeply understand the function of DEGs overexpressing GATA3, which is involved in the occurrence and development of breast cancer." (PMID 30872657, 2019). "We hypothesize that GATA3 promotes the hydrolysis of ATP in the tumor microenvironment and inhibits the metastasis of breast cancer through a GATA3-ENTPD3-eATP axis." (PMID 31754326, 2019). "The downregulation of GATA3 is a strong prognostic marker, especially in the cases of estrogen receptor (ER)-negative breast cancers, and is linked with aggressiveness and poor survival." (PMID 31614829, 2019). "Additionally, GATA3 expression in breast cancer was relatively higher than in any other normal tissue or cancer type in the pan-cancer profile." (PMID 30872657, 2019). "For example, a GATA3 motif was identified through analysis of TCF7L2 ChIP-seq peaks from breast cancer cells; follow-up studies demonstrated that GATA3 and TCF7L2 interact with each other and that depletion of GATA3 in breast cancer cells reduces binding of TCF7L2 to specific sites." (PMID 30866492, 2019). "The results of bioinformatics analyses revealed a close correlation between GATA3 and UTX, and GATA3 has emerged as a strong predictor of tumor differentiation and clinical outcome in breast cancer;1,21 therefore, we focused on the relationship between GATA3 and UTX." (PMID 31685800, 2019).